NSUN5P2 (NSUN5 pseudogene 2)
Description:
May have S-adenosyl-L-methionine-dependent methyl-transferase activity.
Synonyms: WBSCR20B; WBSCR20C; MGC15057; FLJ11626; DKFZp434K058; NOL1R2; formerly NSUN5C
Gene: Transcribed unprocessed pseudogene on chromosome 7 (72,948,485 to 72,954,717, reverse strand). Ensembl gene ENSG00000106133.
Diseases named in the same sentence as NSUN5P2 in open-access papers:
NSUN5P2 is named in the same sentence as 3 diseases in open-access papers, as found by Europe PMC text mining. Sharing a sentence is not in itself a finding about the gene and the disease. The quoted sentences say what the papers report.
endometrial cancer (1 paper, 2025). Primary or metastatic malignant neoplasm involving the endometrium (mucous membrane that lines the endometrial cavity). "The levels of both NSUN5P2 and DLC1 in the tissues of 546 endometrial cancer patients showed significant differences compared to those in the normal control group." (PMID 40708858, 2025). "Upon searching the ULCAN website, we further discovered that the levels of both NSUN5P2 and DLC1 in the tissues of 546 endometrial cancer patients showed significant differences compared to those in the normal control group." (PMID 40708858, 2025).
hepatocellular carcinoma (1 paper, 2022). A malignant tumor that arises from hepatocytes. "For example, NSUN5P2 was found to be unfavorable for the prognosis of hepatocellular carcinoma through bioinformatic analysis." (PMID 36272991, 2022).
tumor (3 papers, 2018 to 2025). "RNA sequencing indicates that NSUN5P2, Linc01694, and DLC1 in differential genes are associated with the cell cycle and the enhancement or inhibition of tumor cell proliferation and invasion, respectively." (PMID 40708858, 2025). "In this study, we constructed a risk score system of three lncRNAs (LOC101927051, LINC00667 and NSUN5P2) for predicting the prognosis of small hepatocellular carcinoma (sHCC) (maximum tumor diameter ≤5 cm)." (PMID 30018179, 2018). "Except for GVINP1 and NCF1C, the expression of the other 5 prognosis-related DE pseudogenes (DDX12P, FER1L4, NSUN5P2, PLEKHA8P1 and RP9P) were higher in tumor tissues than in cutting edge normal tissues, which was totally consistent with the results of TCGA samples." (PMID 36272991, 2022).